S1PR2 (sphingosine-1-phosphate receptor 2)
Diseases named in the same sentence as S1PR2 in open-access papers (continued):
Sharing a sentence is not in itself a finding about the gene and the disease.
ischemia (4 papers, 2017 to 2022). A hypoperfusion of the BLOOD through an organ or tissue caused by a PATHOLOGIC CONSTRICTION or obstruction of its BLOOD VESSELS, or an absence of BLOOD CIRCULATION. "The results of this study showed that S1PR2 expression was significantly increased in pericytes of rats with ischemia and reperfusion." (PMID 34224319, 2021). "Because genetic EC-S1pr2 deficiency can enhance angiogenesis and improve blood flow recovery after ischemia, we next tested whether pharmacological inhibition of S1pr2 had a beneficial effect on hindlimb ischemia." (PMID 35836816, 2022). "This work aimed to analyze the regulatory effect of miR-149-5p on pericytes S1PR2 after acute ischemia reperfusion in rats and whether it was involved in the neuroprotective mechanism, so as to provide reference basis for the treatment of late nervous system diseases." (PMID 34224319, 2021). "TNF-α-induced impairment of cerebrovascular function that associates to CBF deficits and secondary ischemia during SAH are thought to stem from altered S1P signaling as TNF-α alters S1P degradation, which leaves more S1P available for pro-constrictive S1PR2 signaling in mural cells." (PMID 32117979, 2020).
ischemic stroke (4 papers, 2021 to 2023). A stroke disorder caused by obstruction of blood flow to the brain, due to thrombotic (local blood clot formation) or embolic (due to a blood clot or other material traveling from another site) event. "S1PR2 could activate the cytoskeleton contraction mechanism to play a role in increasing capillary permeability, and S1PR2 expression would significantly increase in endothelial cells after ischemic stroke, leading to neurovascular injury." (PMID 34224319, 2021). "S1P is the ligand protein for S1PR and has been identified to bind to S1PR1, S1PR2, and S1PR3 to trigger neuroinflammatory reactions in ischemic stroke." (PMID 35055089, 2022).
lung carcinoma (4 papers, 2022 to 2025). "In lung cancer, S1PR2 exhibits context-dependent effects, functioning as both as a tumor-suppressor and a tumor-promotor." (PMID 41511294, 2025). "We found that lung cancer tissues expressed mainly S1PR1, S1PR2 and S1PR3, whereas S1PR4 and S1PR5 were undetectable, probably because they are highly restricted to distinct cell types and tissues, such as the lymphoid tissues, brain, and spleen." (PMID 37446018, 2023). "Indeed, we demonstrated that S1PR1, S1PR2, S1PR3, and S1PR5, but not S1PR4 are correlated with worse lung cancer patient prognosis." (PMID 35897763, 2022).
Obesity (4 papers, 2017 to 2024). Accumulation of substantial excess body fat. "DCA can stimulate the expression of S1PR2, regulate the protein kinase (ERK) signali pathway, and induce the activation of NLRP3 inflammasomes, which is one of the causes of chronic inflammation caused by obesity." (PMID 35845812, 2022).
ovarian carcinoma (4 papers, 2017 to 2023). A malignant neoplasm originating from the surface ovarian epithelium. "In a complementary approach, we used siRNAs specific to SPHK1, S1PR1, and S1PR2 to knock down those proteins’ expression in ovarian cancer cells." (PMID 35289120, 2022). "In ovarian cancer, we observed that 55% (11/20) samples displayed high S1PR1 level, 80% (16/20) samples showed high S1PR2 level and 75% (15/20) samples showed high S1PR3 level." (PMID 29088837, 2017). "We previously found that S1PR1, S1PR2 and S1PR3 were overexpressed in ovarian cancer tissue." (PMID 33931106, 2021). "We found that S1PR1 and S1PR3, but not S1PR2, were responsible for the angiogenic potential and angiogenic factor secretion of ovarian cancer cells in vitro." (PMID 29088837, 2017). "Our results showed that down-regulation of S1PR1 or S1PR3, but not S1PR2, effectively inhibited S1P-induced VEGF, IL-8 and IL-6 secretion in ovarian cancer cells." (PMID 29088837, 2017).
adenoma (3 papers, 2020 to 2022). A neoplasm arising from the epithelium. "S1PR2 immune-histochemical analysis in intestinal tissue of Apcmin/+ mice revealed a strong decrease of the receptor in the epithelial compartment of both high-grade adenomas and carcinomas compared to the normal epithelium." (PMID 33225975, 2020). "Our current observations revealed: i) a not significant modulation of S1P levels in CRC patients; ii) higher expression of S1PR1 among the receptors in the normal mucosa; iii) a marked decrease only of S1PR2 in primary CRC already at an early phase (adenoma) of tumor development." (PMID 33225975, 2020). "Moreover, while vehicle-treated Apcmin/+ mice developed only low-grade adenomas, the Apcmin/+ mice treated with the JTE013 inhibitor broadened high-grade adenomas and carcinomas, corroborating the loss of S1PR2 as an accelerator of tumor development and de-differentiation." (PMID 33225975, 2020). "All adenoma samples showed a significant reduction of S1PR2 compared to healthy mucosa, thus corroborating the hypothesis that the loss of S1PR2 in the epithelial compartment plays a key role in colorectal tumorigenesis and that it likely occurs in the early phase of cancer development." (PMID 33225975, 2020).
bladder cancer (3 papers, 2019 to 2024). "as it was reported that the expression of S1P receptors, S1PR1, S1PR2 and S1PR3 is linked to the pathological grades and stages of bladder cancer." (PMID 39315290, 2024).
Cognitive impairment (3 papers, 2021 to 2023). Abnormal cognition is characterized by deficits in thinking, reasoning, or remembering. "in In hyperammonemic rats, we assessed if blocking S1PR2 reduced hippocampal neuroinflammation and reversed cognitive impairment and if the signaling pathways were involved." (PMID 38139078, 2023). "The S1PR2 is expressed in hippocampal pyramidal/granular neurons, and mice lacking this receptor have a high rate of spontaneous seizures and cognitive deficits." (PMID 35501309, 2022). "Moreover, downregulation of Nogo-A led to alleviation of the cognitive impairment and microvascular dysfunction as well as the inhibition of the expression of S1PR2 and the RhoA/ROCK signaling pathway." (PMID 34830564, 2021).
oral squamous cell carcinoma (3 papers, 2016 to 2023). "The effects of S1P/S1PR2 are cell type dependent; and it has been reported to induce tumour suppression in human anaplastic thyroid cancer, glioblastoma, B16 melanoma and neuroblastoma cells but also to accelerate metastasis of human adenocarcinoma and oral squamous cell carcinoma (OSCC) cells." (PMID 37038210, 2023). "In addition, an S1P antagonist, CYM-5478, may promote tumor aggressiveness by targeting S1PR2 in oral squamous cell carcinoma." (PMID 31807117, 2019).
pancreatic cancer (3 papers, 2015 to 2023). "Additionally, taurocholic acid TCA, a conjugated BA, was found to accelerate the growth of S1PR2-overexpressing pancreatic cancer both in vitro and in vivo, suggesting that S1PR2 may be a potential therapeutic target in cancer." (PMID 38203175, 2023).
psoriasis (3 papers, 2021 to 2024). An autoimmune condition characterized by red, well-delineated plaques with silvery scales that are usually on the extensor surfaces and scalp. "Recent studies have found that several S1PR functional antagonists, other than S1PR2, are effective in improving psoriasis." (PMID 39391307, 2024). "Although there has been little research on the mechanism by which S1PRs other than S1PR1 affect psoriasis, it has been reported that S1PR2 gene expression is elevated in the skin of mice in which a Western diet activates the Th17 pathway." (PMID 37830566, 2023). "In addition, a GWAS study showed that only S1PR1 gene expression decreases in the lesional skin of psoriasis patients compared to non-lesional skin, with no change in the S1PR2-5 gene expression." (PMID 37830566, 2023).
ulcerative colitis (3 papers, 2022 to 2024). An inflammatory bowel disease involving the mucosal surface of the large intestine and rectum. "In fact, two S1PR2 inhibitors, Etrasimod and Ozanimod have demonstrated potential as treatment options for individuals with ulcerative colitis, further highlighting the complexity of S1PR2 signaling in intestinal inflammation." (PMID 36569849, 2022). "However, the specific function of S1PR2 in intestinal diseases, such as ulcerative colitis (UC), remains unclear." (PMID 35707833, 2022).
Wilms tumor (3 papers, 2013 to 2025). An embryonal neoplasm characterized by the presence of epithelial, mesenchymal, and blastema components. "An association between CTGF and S1PR2 has been reported in Wilms' tumor." (PMID 24744854, 2013). "In Wilms tumor, S1PR2 was found to contribute to tumor growth and angiogenesis by stimulating the expression of cyclooxygenase 2 (COX-2)." (PMID 31807117, 2019). "In the Wilms’ tumor cell line (WiT49), S1P was shown to induce COX2 expression through S1PR2 leading to PGE2 production." (PMID 40857274, 2025).
acute liver failure (2 papers, 2017 to 2022). Rapid deterioration of liver function causing encephalopathy and coagulopathy. "This research may help identify if bile acid-mediated S1PR2 signaling could be a therapeutic target for management of neuroinflammation during HE due to acute liver failure." (PMID 28725183, 2017). "Thus, reducing levels of bile acids or antagonizing S1PR2 activity may be potential treatment modalities for the management of HE due to acute liver failure." (PMID 28725183, 2017). "At this time no data exist concerning the role of S1PR2-mediated signaling in the brain due to increased bile acid concentrations following acute liver failure." (PMID 28725183, 2017).
acute pancreatitis (2 papers, 2022 to 2024). An acute inflammatory process that leads to necrosis of the pancreatic parenchyma. "In the current study, we report that activation of S1PR2 plays an essential role in NF-κB activation in acinar cells and macrophages under acute pancreatitis conditions." (PMID 36229875, 2022). "We also demonstrated that blockade of S1PR2 alleviated Ly6G + neutrophil infiltration in acute pancreatitis mice." (PMID 36229875, 2022). "Here, we focused on exploring the influence of S1PR2 on the early inflammatory response within acinar cells under acute pancreatitis conditions." (PMID 36229875, 2022). "Based on previous studies, S1PR2 is an interesting target for pancreatic systemic inflammatory responses during acute pancreatitis and is worth further study." (PMID 36229875, 2022). "The significant increase in S1PR2 expression in the acute pancreatitis model prompted us to elucidate the function of S1PR2 in acute pancreatitis." (PMID 36229875, 2022). "The chemical antagonist of S1PR2, JTE-013, and AAV-mediated knockdown of S1PR2 also showed protective effects against acute pancreatitis in vivo." (PMID 36229875, 2022). "In conclusion, these findings open new perspectives for S1PR2 as a target for the treatment of acute pancreatitis." (PMID 36229875, 2022). "Taken together, these results prove that S1PR2 knockdown may be an excellent therapeutic strategy for acute pancreatitis via alleviating pancreatic injury." (PMID 36229875, 2022). "Finally, blockade of S1PR2 by JTE-013 also showed a protective effect against acute pancreatitis in vivo." (PMID 36229875, 2022). "First, we examined whether blockade of S1PR2 expression could affect the initiation and progression of acute pancreatitis." (PMID 36229875, 2022). "We examined the expression of S1PR2 in these two experimental acute pancreatitis models." (PMID 36229875, 2022). "In the present study, we identified a critical role of S1PR2 in acute pancreatitis." (PMID 36229875, 2022). "Furthermore, our results support that S1PR2 blockade can alleviate the early inflammatory response and provide new compelling therapeutic information for acute pancreatitis." (PMID 36229875, 2022). "Here we report that S1PR2 was upregulated in the whole pancreas during acute pancreatitis." (PMID 36229875, 2022). "Overall, this study highlighted that S1PR2 is the critical role in acute pancreatitis." (PMID 36229875, 2022). "Our study suggests that targeting S1PR2-mediated signaling pathways may have therapeutic potential for a subset of acute pancreatitis that currently lacks effective therapies." (PMID 36229875, 2022). "To determine whether S1PR2 mediated sustained pathological inflammation in vivo, we subjected mice to intraperitoneal injection of S1PR2-shRNA S1PR2-shRNA markedly and specifically downregulated S1PR2 expression in the pancreas of acute pancreatitis mice." (PMID 36229875, 2022). "In addition, the immunofluorescence results indicated that positive S1PR2 staining was obviously upregulated in acute pancreatitis mice by either caerulein or taurocholate, and most of the anti-S1PR2 staining is localized at the acinar cells." (PMID 36229875, 2022). "The specific antagonist of S1PR2, JTE-013, was injected to mice 1 h before acute pancreatitis induction." (PMID 36229875, 2022). "We analyzed the expression of S1PR2 in isolated primary peritoneal macrophages and RAW264.7 cells in acute pancreatitis models." (PMID 36229875, 2022). "As expected, administration of the S1PR2 antagonist JTE-013 resulted in a lower number of infiltrating macrophages and lower levels of inflammatory factors during acute pancreatitis in vivo." (PMID 36229875, 2022). "Blockade of S1PR2 by pharmacologic inhibition of S1PR2 by JTE-013 or AAV-mediated knockdown of S1PR2 improved the severity of pancreatic injury, as indicated by a significant reduction in inflammation and acinar cells death in acute pancreatitis mice." (PMID 36229875, 2022).
acute pancreatitis (continued). "However, the role of S1PR2 in inflammatory signaling activation within acinar cells and inflammatory responses during acute pancreatitis has not been elucidated." (PMID 36229875, 2022). "In pancreatic acinar cells, activation of S1PR2 by TCA promotes NF-κB transactivation through the ROCK signal pathway, leading to the secretion of inflammatory factors, further recruiting immune cell, especially macrophages, and promoting M1 phenotype polarization during acute pancreatitis." (PMID 36229875, 2022).
Allergy (2 papers, 2022 to 2025). An allergy is an immune response or reaction to substances that are usually not harmful. "Since S1PR2 is involved in allergic inflammation, the identification of the downstream targets of S1PR2 is necessary for developing anti-allergy drugs." (PMID 36430378, 2022). "The identification of more chemicals that can bind to IL-4R and/or S1PR2 might give clues for developing anti-allergy therapeutics." (PMID 40005151, 2025). "S1PR2 signaling can induce airway T cell infiltration in mouse models of acute allergic reactions." (PMID 40005151, 2025).
Autoimmunity (2 papers, 2014 to 2024). The occurrence of an immune reaction against the organism's own cells or tissues. "Since S1PR2 plays pivotal roles in CNS autoimmunity, cell differentiation, and enhancement of BBB permeability and leukocyte entry, we also measured protein levels of S1PR2." (PMID 38916732, 2024). "S1PR2 signaling at the BBB may prove to be a particularly attractive therapeutic target, due to its recently discovered contribution to sexually dimorphic patterns of CNS autoimmunity." (PMID 26556427, 2014).
autosomal recessive hearing loss (2 papers, 2016 to 2018). "Only two reported pathogenic variants (c.323G>C, p.Arg108Pro and c.419A>G, p.Tyr140Cys) in the S1PR2 gene have previously been linked to autosomal recessive hearing loss (DFNB68) in two Pakistani families." (PMID 29776397, 2018).
E. coli infection (2 papers, 2016 to 2019). "S1PR2 promoted macrophage pyroptosis, which is linked to a cytokine storm, upon E. coli infection, while a S1PR2 knockout improved survival." (PMID 31379883, 2019).
esophageal cancer (2 papers, 2021 to 2022). A primary or metastatic malignant neoplasm involving the esophagus. "In accordance with this, another study also confirmed the pro-tumor role of S1PR2 in esophageal cancer." (PMID 34831211, 2021). "Contrary to the pro-tumor roles of S1PR1, S1PR2, and S1PR3, S1PR5 was claimed to exert inhibitory effects on the proliferation and migration of esophageal cancer via the Ras/ERK, PI3K/Rac and Rho/ROCK signaling pathways." (PMID 34831211, 2021).
experimental autoimmune encephalomyelitis (2 papers, 2015 to 2025). An autoimmune demyelinating disease of the central nervous system that is produced experimentally in animals by the injection of homogenized brain or spinal cord in Freund's adjuvant. "In contrast, sphingosine-1-phosphate receptor 2 has been identified as a sex- and strain-specific modulator of BBB permeability in female rodent models of experimental autoimmune encephalomyelitis." (PMID 40624697, 2025).
inflammatory bowel disease (2 papers, 2019 to 2025). A spectrum of small and large bowel inflammatory diseases of unknown etiology. "This scenario is in agreement with recent reports indicating that S1PR2 exerts a damaging effect on intestinal vascular endothelial barrier function and macrophages in inflammatory bowel disease." (PMID 39854311, 2025). "The anti-inflammatory function of S1PR2 was also discovered in inflammatory bowel disease, as data showed that miR-126 could down-regulate S1PR2 expression and thus inhibit the activation of its downstream pathway PI3K/AKT signal pathway." (PMID 31791242, 2019).
leukemia (2 papers, 2016 to 2022). A malignant (clonal) hematologic disorder, involving hematopoietic stem cells and characterized by the presence of primitive or atypical myeloid or lymphoid cells in the bone marrow and the blood. "To target the tumor suppressive SMAD1/S1PR2 pathway and the leukemia-supporting IRE1/XBP1s pathway, we used the S1PR2 agonist CYM-5520 and the IRE1 inhibitor B-I09, respectively." (PMID 36042317, 2022).
lung disease (2 papers, 2014 to 2025). "Advancing our knowledge in S1PR2 biology holds promise for the development of novel therapies aimed at mitigating lung injury and restoring homeostasis in a range of pulmonary diseases." (PMID 41511294, 2025). "Building on these mechanistic insights, the following section examines how S1PR2 contributes to the pathogenesis of multiple pulmonary diseases." (PMID 41511294, 2025). "Here, we examine mechanistic insights into S1PR2 signaling, define its context-dependent functions, and evaluate its potential as a therapeutic target in lung disease." (PMID 41511294, 2025). "While S1P itself and S1PR1 have been extensively studied as targets for lung disorders, the functions of S1PR2 remain comparatively underexplored despite growing evidence that it plays a critical role in pulmonary biology." (PMID 41511294, 2025). "The findings of this study could help develop new strategies for treating pulmonary disorders and other diseases by targeting S1PR2." (PMID 41511294, 2025).
non-alcoholic fatty liver disease (2 papers, 2018 to 2023). "With regard to S1P and S1PRs in pathophysiology in the liver, it has been demonstrated that S1P is involved in hepatic insulin resistance via S1PR2, and enhances hepatic lipid storage via S1PR2 and S1PR3, and S1PR1 is responsible for the non-alcoholic fatty liver disease." (PMID 30543684, 2018).
oesophageal cancer (2 papers, 2013 to 2022). "Alternatively, high expression of S1PR2 on mesenchymal-like oesophageal cancer cells is associated with the invasive phenotype in this highly acidic gastroesophageal reflux environment." (PMID 35158806, 2022). "Hence the suggestion that targeting S1PR2 with a specific S1PR2 antagonist, JTE-013, may be a potential adjunct therapy for these types of oesophageal cancers." (PMID 35158806, 2022).